LINC02770 (long independently transcribed non-coding RNA 2770)
Gene: Long non-coding RNA gene on chromosome 1 (191,823,432 to 192,011,260, forward strand). Ensembl gene ENSG00000228215.
Diseases named in the same sentence as LINC02770 in open-access papers:
LINC02770 is named in the same sentence as 2 diseases in open-access papers, as found by Europe PMC text mining. Sharing a sentence is not in itself a finding about the gene and the disease.
LINC02770 shares sentences with these, for which no sentence is quoted: insomnia (1 paper); post-traumatic stress disorder (1).